RIPK3 (receptor interacting serine/threonine kinase 3)
Diseases named in the same sentence as RIPK3 in open-access papers (continued):
Sharing a sentence is not in itself a finding about the gene and the disease.
infection (146 papers, 2014 to 2025). The state of being infected such as from the introduction of a foreign agent such as serum, vaccine, antigenic substance or organism. "To determine and compare the effect of RIPK3 or MLKL-deficiency during late stages of LCMV docile infection, we measured the virals loads in the lung, liver, spleen, kidney and brain at 8, 35 and 100 days post infection." (PMID 36792599, 2023). "We found that Casp1/11+/–Casp8–/–Ripk3–/– mice largely phenocopied WT B6 mice, and were resistant to infection, exhibiting minimal weight loss, diarrhea, cecal or colonic shrinkage, and no fecal blood." (PMID 36645406, 2023). "Strikingly, C. rodentium-infected Casp8–/–Ripk3–/–Casp1/11–/– mice showed severe body weight loss and died within 12 dpi, while the other cohorts survived the infection." (PMID 37080966, 2023). "While we identify dysregulated type 1 interferon signaling as potential mechanism, a thorough analysis of IFN-I levels in RIPK3-deficient mice across numerous infections is warranted to help unravel the complexities caused by RIPK3’s multiple roles." (PMID 36792599, 2023). "Using ex vivo peptide re-stimulation, there was a comparable loss of cytokine producing virus-specific CD8+ T across Ripk3−/−, Mlkl−/− and WT animals at both day 8- and 35-post infection." (PMID 36792599, 2023). "We do observe that Casp1/11–/–Casp8+/–Ripk3–/– are modestly susceptible to infection while Casp1/11+/–Casp8–/–Ripk3–/– mice are fully resistant." (PMID 36645406, 2023). "We isolated thioglycolate-illicited primary macrophages from uninfected animals and found that Ripk3−/− macrophages were equally susceptible to LCMV infection compared to WT macrophages following 24 h of ex vivo infection." (PMID 36792599, 2023). "Ripk3-deficient mice also exhibited worsened clinical disease prior to death, as evidenced by earlier and more dramatic weight loss following infection." (PMID 38011306, 2023). "Passive transfer with anti-M2e monoclonal antibodies was shown to limit viral load in the infected lungs which can modulate the susceptibility of the Ripk3−/− mice to the IAV making them less susceptible to the same dose of infection." (PMID 35351865, 2022). "Ripk3-mediated necroptosis is a hallmark feature of cellular clearance of infection and plays a key role in immunity and inflammation." (PMID 35561683, 2022). "RIPK3-deficiency interfered with the secretion of certain cytokines upon MVA-infection as well as with constitutive CCL2-secretion." (PMID 34711816, 2021). "ZBP1-/RIPK3-deficient mice are hypersusceptible to lethal infection caused by IAV, failing to control IAV replication and succumbing to lethal respiratory infection." (PMID 34594225, 2021). "For the medium viral dose of infection (0.2x LD50/16 pfu) the susceptibility of Ripk3−/− mice is significantly potentiated (p value= 0.0218) compared to Ripk3+/+ littermates." (PMID 33976111, 2021). "We do not observe any shift in the bodyweight loss curve for the other infection doses suggesting that RIPK3 only affects the mortality threshold (i.e. the ethical endpoint) of the mice." (PMID 33976111, 2021). "Casp8/Ripk3/Casp1/11−/− mice were significantly more susceptible to lethal infection with WT B. thailandensis than were WT mice." (PMID 34154417, 2021). "Here, we show that RIPK3 deficiency negatively impacts the control of LM-OVA burden only at the early stage (day 3) of infection." (PMID 32328060, 2020). "Following infection, noninvasive S. Typhimurium caused ∼25% death in both wild-type (WT) and Ripk3−/− bone marrow-derived macrophages (BMDMs), based on ATP quantification and lactate dehydrogenase (LDH) release." (PMID 33024046, 2020). "Consistent with the implicated role of virus-induced necroptosis in restricting infection, viral pathogenesis is restored in Zbp1−/−, Ripk3−/− and Mlkl−/− mice." (PMID 30050136, 2018).
infection (continued). "In response to infection, the proportion of Ripk3Δintron2 HSPCs was increased relative to WT cells, indicating a cell-intrinsic role for RIPK3 in the infection-induced loss of HSPCs." (PMID 30080899, 2018). "Such pathways reportedly contribute to protection against certain infections such as influenza A virus, with Ripk3−/− mice experiencing a heightened susceptibility to infection due to an inability of macrophages to produce type I IFN in the lungs." (PMID 29892302, 2018). "The correlations between the plasma RIPK3 level and other infection-associated biomarkers were determined." (PMID 29137405, 2017). "We have found that influenza A virus (IAV)-mediated cell death is largely reliant on RIPK3 and that RIPK3-deficient mice are notably more susceptible to lethal infection by IAV than their wild-type counterparts." (PMID 27391363, 2016). "In addition, HCMV vICA contributes to resistance to caspase-independent death during infection being implicated in the suppression of virus-induced RIPK3-dependent necroptosis." (PMID 39772130, 2024). "Additionally, a thorough comparison of infection phenotypes across RIPK3 and MLKL-deficient mice is essential in all future studies attempting to attribute clinical outcomes to RIPK3 versus necroptosis." (PMID 36792599, 2023). "A conundrum with our data is that viral loads fall at the late stages of persistent infection in RIPK3-deficient mice compared to WT animals but the absolute number of effector immune cells capable of clearing infection is similar between genotypes at this time." (PMID 36792599, 2023). "They found that RIPK3-deficient animals had impaired infection control and increased inflammation." (PMID 37409125, 2023). "Herein, reduced IL-1β secretion and pyroptosis observed in Casp8/RIPK3−/− mice are possible mechanisms that may contribute to increased susceptibility to infection." (PMID 36532444, 2022). "Subsequent studies have shown that cells deficient in caspase-1/-11 or caspase-8/RIPK3 still undergo cell death in response to the infection, while cells deficient in caspase-1/-11/-8/RIPK3 or cells deficient in caspase-1/-11/-12/-8/RIPK3 are protected from cell death." (PMID 35563804, 2022). "Interestingly, already at a low dose of infection (0.1x LD50/8 pfu) Ripk3−/−Fadd−/− DKO mice showed enhanced susceptibility to IAV compared to their littermates (p value= 0.0878) and compared to RIPK3-deficient mice (p value =0.0066)." (PMID 33976111, 2021). "The biological function of RIPK3 appears to be important only for the natural route of T. gondii infection, as there is not a difference in susceptibility between WT and RIPK3−/− mice after i.p. infections." (PMID 33526566, 2021). "Knockout mice deficient of RIPK3 were highly susceptible to infection with HSV-1 and poxvirus." (PMID 33796483, 2021). "The failure of Casp8/Ripk3/Casp1/11−/− BMDMs to restrict B. thailandensis intercellular spread via cell-cell fusion and intracellular replication suggested that Casp8/Ripk3/Casp1/11−/− mice would be highly susceptible to severe lethal infection." (PMID 34154417, 2021). "Furthermore, infection of double-deficient (RIPK3–/– Casp-1/11–/–) mice with ST-OVA results in a higher frequency of IFN-γ-producing CD8+ T cells." (PMID 32328060, 2020). "Interestingly, they also showed that the levels of type I IFN, although modest, were significantly reduced in RIPK3-deficient fibroblasts after infection with IAV." (PMID 28410401, 2017). "Ripk3-/-Casp8-/- mice also had equivalent levels of cytokine responses in the lung, similar viral burdens, and similar kinetics of weight loss over the course of the infection." (PMID 27737018, 2016). "The source of these cytokines remains to be identified, however the increase in dendritic cells (DCs) we observed in RIPK3-deficient animals during the intermediate phase of infection might provide clues, given dendritic cells are also known to produce high amounts of type I IFN." (PMID 36792599, 2023).
infection (continued). "Given our observation that PANoptosis-deficient BMDMs (Casp8/Ripk3/Casp1/11−/−) displayed distinct cell death activation kinetics during B. thailandensis infection, we biochemically examined the activation of pyroptotic, apoptotic, and necroptotic pathways at 24 h of infection." (PMID 34154417, 2021). "Additionally, Casp8/Ripk3/Casp1/11−/− mice, which are deficient in PANoptosis, allow the study of the combined roles of pyroptosis, caspase-8-dependent apoptosis, and necroptosis during infection." (PMID 34154417, 2021). "Thus, to determine whether RIPK3 deficiency impacted on intracellular Mtb burdens during physiological infection in vivo, we isolated alveolar macrophages from the lungs of Mtb-infected mice by BAL and assessed intracellular CFU by plating cell lysates." (PMID 29892302, 2018). "For example, the bacterial effector OspD3, secreted by Shigella flexneri, cleaves host kinases RIPK1 and RIPK3 to evade necroptosis-mediated immune responses during infection." (PMID 40424468, 2025). "Given that O. tsutsugamushi expresses ank1 and ank6 throughout infection of host cells, we assessed if the pathogen lowers RIPK3 levels." (PMID 40430799, 2025). "To further confirm if the upregulation of MLKL during the early stages of infection was dependent on RIPK3, we conducted the time course experiment in a RIPK3‐deficient cell line HeLa." (PMID 40490945, 2025). "The results showed that the levels of phosphorylated MLKL, RIPK1, and RIPK3, and cytotoxicity were higher in cells infected with ΔospD3 than in cells infected with WT Shigella, indicating that ΔospD3 infection triggers necroptosis." (PMID 40931196, 2025). "In HEC-LTT/RIPK3 cells, we observed a similar modulation of the necrosome components after infection with TB40/E, however, the kinetics appeared to be different compared to TB40/E-infected HFF cells." (PMID 38400065, 2024). "ZBP1 is found to interact with RIPK3 and thereby promotes the execution of necroptosis during infection with HSV-1, MCMV and influenza A virus." (PMID 38400065, 2024). "In vivo, Ripk3−/− mice and Zbp1−/− mice were reported to be more susceptible to IAV PR8 (H1N1 strain) infection compared to wild type mice, exhibiting elevated pulmonary viral load and heightened morbidity and mortality." (PMID 38778049, 2024). "Our study demonstrates a critical role for Casp8 in preventing infection and inflammation-induced Ripk3-mediated necroptosis in HSPCs." (PMID 38637559, 2024). "Corresponding to the magnitudes of cell death observed in Oasl1+/+ and Oasl1–/– fibroblasts, MCMV-M45mutRHIM infection-induced RIPK3 phosphorylation was drastically reduced in Oasl1–/– fibroblasts compared with Oasl1+/+ fibroblasts (left)." (PMID 36604592, 2023). "We next gavaged Casp8+/-Ripk3–/– and Casp8–/–Ripk3–/– cohorts with C. rodentium to evaluate the role of caspase-8 during an in vivo infection." (PMID 37080966, 2023). "Together, these data suggested that the enhanced pathogenesis observed in Ripk3-/- mice was due to a specific failure to control infection in neurons of the cerebellum, resulting in enhanced overall CNS viral burden." (PMID 38011306, 2023). "Assessment of viral burdens in brains of Ripk3-/- mice following subcutaneous LGTV infection revealed that Ripk3-/- mice exhibited significantly elevated CNS viral titers, particularly in the cerebellum, at both 8 and 12 dpi." (PMID 38011306, 2023). "M45 contains a RHIM and inhibits RIPK3 through RHIM-dependent interaction during infection to suppress the ZBP1‐RIPK3‐dependent necroptosis." (PMID 37012234, 2023). "To assess this, we next used an intracranial infection route in order to assess local effects of RIPK3 signaling on LGTV pathogenesis." (PMID 38011306, 2023). "Although both cohorts displayed similar weight changes, Casp8–/–Ripk3–/– mice continued shedding pathogens in their feces until 35 dpi, one week after their Casp8+/-Ripk3–/– littermates had already cleared the infection." (PMID 37080966, 2023).
infection (continued). "In contrast, Casp8+/-Ripk3–/–Casp1/11–/– mice disabled for necroptosis and pyroptosis cleared the infection with normal kinetics, in line with the ability of Gsdmd–/–Mlkl–/– mice to clear intestinal C. rodentium loads." (PMID 37080966, 2023). "Although Ripk3–/– mice exhibited slightly reduced footpad swelling than WT mice upon MCMV-WT infection, they showed peak footpad swelling at 6 d.p.i." (PMID 36604592, 2023). "Differences in viral burden did not appear to be linked to deficits in blood-brain barrier integrity, as both Ripk3-/- mice and littermate controls exhibited similar levels of sodium fluorescein extravasation into the CNS following infection." (PMID 38011306, 2023). "At the same early time of 12 h post-infection, the RIPK3 KO BMDMs started to diverge from the ZBP1 KO cells and began to show the activation of caspases and GSDMD and GSDME." (PMID 38005819, 2023). "Oasl1–/– primary fibroblasts reconstituted with haemagglutinin-tagged OASL1 (HA–OASL1) formed discrete cytosolic condensates after MCMV-M45mutRHIM infection that precisely colocalized with phospho-RIPK3-positive foci." (PMID 36604592, 2023). "For instance, it was shown that both Casp1/11–/– and Casp8–/–Ripk3–/– mice resisted an intravenous Salmonella Typhimurium infection, while Casp8–/–Ripk3–/–Casp1/11–/– mice succumbed to this infection." (PMID 37080966, 2023). "It has been shown in mice that ZBP1/DAI is a RHIM adaptor able to recruit RIPK3 to drive virus-induced necroptosis during infection with RHIM suppressor mutant herpesviruses." (PMID 37083451, 2023). "In order to examine the role of necroptosis on CD8+ T cell number and function during chronic LCMV infection, we infected RIPK3 and MLKL-deficient animals and performed analyses at days 8 and 35 post infection." (PMID 36792599, 2023). "Intrestingly, there was a small but transient increase in the numbers of granulocytes, cDCs and B cells in Ripk3−/− mice compared to WT, within the first week post infection." (PMID 36792599, 2023). "At day 8 post infection, we detected a significant decrease in IFNβ levels but only slight decrease in IFNα, in the livers of Ripk3−/− mice compared to control animals." (PMID 36792599, 2023). "We infected mouse primary tail fibroblasts with the necroptosis-sensitive MCMV-M45mutRHIM, and at 6 h post-infection (h.p.i.), endogenous mouse RIPK3 was immune-purified and subjected to mass spectrometry analysis." (PMID 36604592, 2023). "It was previously shown that IAV-specific CD8+ T cell numbers were significantly diminished upon infection in Ripk3−/− mice compared to littermate controls." (PMID 35351865, 2022). "In order to understand the underlying phenomena explaining the difference in vaccination efficiency in Ripk3−/− and Ripk3+/+ mice, we determined immune cells infiltration in the lungs following vaccination and infection." (PMID 35351865, 2022). "Because infection with P. aeruginosa is very severe and harmful in many diseases, we investigated the effect of RIPK3 on P. aeruginosa‐induced acute airway inflammation." (PMID 36226560, 2022). "We infected BMDMs of C57BL/6, Gsdmd−/−, Casp8/RIPK3−/−, and Casp8+/+/RIPK3−/− mouse strains with B. abortus, and after 17 h of infection, we evaluated the secretion of IL-1β in the supernatant of the cells." (PMID 36532444, 2022). "Compared with the wild-type MCMV (MCMVWT), the M45 mutant MCMV (MCMVM45mutRHIM) infection-induced RIPK3-dependent but RIPK1/TRIF-independent necroptosis and show weaker replication in 3T3-SA or SVEC4-10 cells." (PMID 36142136, 2022). "THP-1 and RAW264.7 cells were pre-treated with ZVAD-FMK (40 μM), Nec-1s (50 μM), and GSK’872 (20 nM), the inhibitors for pan-caspases, RIPK1, and RIPK3, respectively, followed by infection with ZIKV." (PMID 35446851, 2022). "RHIM-mediated signaling by RIPK1, TRIF, ZBP1, and RIPK3 culminating in necroptosis is a key pathway utilized by cells in inflammation and infection settings." (PMID 36040212, 2022).
infection (continued). "Mice deficient in ZBP1 and RIPK3 show increased paralysis upon peripheral ZIKV infection and rapid mortality upon direct infection of the CNS, indicating the possible role of these necroptotic components." (PMID 35587190, 2022). "Our results show that the expression levels of RIPK3 in post-infection tracheal and renal tissues gradually rose with the increasing duration of infection and NIBV activates RIPK3-driven necroptosis." (PMID 36016369, 2022). "Almost all Ripk3−/− mice, though vaccinated died soon after infection, while most Ripk3+/+ littermates survived." (PMID 35351865, 2022). "RIPK3 is a serine-threonine protein kinase that is a key regulator of infection-induced necroptosis, which plays different roles in different types of tumors." (PMID 36046241, 2022). "HSV1-encoded ICP6 prevents receptor-interacting protein kinase 3 (RIPK3)-mediated necroptosis during infection of human cells, but it also acts as a species-dependent inducer of necroptosis in murine cells and thereby restricts virus replication." (PMID 36121858, 2022). "HSV1 has been shown to replicate to higher amounts in Ripk3-/- mouse cells and in Ripk3-/- mice, thereby implicating RIPK3-mediated necroptosis in host control over infection." (PMID 36121858, 2022). "mRNA expression levels of caspase-8 and receptor-interacting kinase-3 (RIPK3) were upregulated >10-fold after infection." (PMID 35215199, 2022). "While Casp8/Ripk3/Casp1/11−/− BMDMs were protected from cell death in the early stage of infection with B. thailandensis, this delay in cell death resulted in increased formation of MNGCs via cell-cell fusion." (PMID 34154417, 2021). "RIPK1 and RIPK3 were slightly increased upon infection in the livers of uninfected and Lm-infected OTUB1FL and OTUB1LPC-KO mice." (PMID 33712742, 2021). "Casp8/Ripk3−/− mice can then be used to study the combined role of the apoptotic and necroptotic pathways during infection with B. thailandensis." (PMID 34154417, 2021). "The failure of MlklK219R/K219R cells to clear MCMVM45mutRHIM infection phenocopies Ripk3−/−, Zbp1−/− and Zbp1ZBDmut infected cells." (PMID 34099649, 2021). "Consistent with mouse survival during infection, WT and Gsdmd−/− mice harbored less B. thailandensis, while Casp1/11−/− and Casp8/Ripk3/Casp1/11−/− mice harbored increased bacteria." (PMID 34154417, 2021). "After oral infection, MLKL−/− mice succumb to infection, similar to WT mice, whereas RIPK3−/− mice showed improved survival." (PMID 33526566, 2021). "Infection with high viral dose (0.5x LD50/40 pfu) leads to 100% lethality in both Ripk3−/− mice and Ripk3+/+ littermates." (PMID 33976111, 2021). "Collectively, these data improve our understanding of pathogen-macrophage interactions, including outcomes of regulated cell death during infection in vivo, and reveal a potential new role for RIPK3 in resolving inflammation." (PMID 33024046, 2020). "The results confirm CA6 infection induced necroptosis (Figure 3D2) compared to mock infection (Figure 3D1), and the increased expression of RIPK3 was visualized in necroptotic cells induced by CA6-infection (Figure 3D4) compared to mock-infection (Figure 3D3)." (PMID 32117097, 2020). "The results indicated that RIPK1 and RIPK3 are involved in the injury process of chicken lungs after infection with P. multocida, and the mechanisms of lung injury induced by different strains are different." (PMID 32286320, 2020). "Our results demonstrate that RIPK3 and Casp-1/11 deficiencies directly impact the clearance of LM-OVA infection." (PMID 32328060, 2020). "Casp1–/–;Casp8–/–;Ripk3–/– iBMDMs responded to the infection by upregulation of caspase-11 and underwent cell death, although this killing was less effective with ∼60%–70% of the cells surviving the bacterial assault." (PMID 32735843, 2020).